IL1B (interleukin 1 beta)
Diseases named in the same sentence as IL1B in open-access papers (continued):
Sharing a sentence is not in itself a finding about the gene and the disease.
E. coli infection (continued). "With P. aeruginosa infection, the TLR8 inhibitor impaired the production of IL-12p70 and IL-1β, while with E. coli infection the inhibitor had less effect that varied depending on the strain and conditions." (PMID 31214180, 2019). "Our findings indicate that E. coli infection activates caspase-4, subsequently resulting in cell pyroptosis and maturation of IL-1β and IL-18 via an NLRP3 inflammasome-dependent and ASC-independent pathway." (PMID 30087667, 2018). "Our previous study has showed that IL-1β, IL-6, and IL-8 in duck and DEFs increase somewhat after E. coli infection." (PMID 30349536, 2018). "Caspase-11 is activated via NLRP3-independent mechanisms, but it is essential for NLRP3-dependent and ASC-dependent caspase-1 processing and IL-1β maturation in response to E. coli infection." (PMID 30087667, 2018). "Compared with untreated control cells, IL-1β production was increased at 3 and 6 h after E. coli infection in WT cells only infected with E. coli (P < 0.001 for both)." (PMID 30087667, 2018). "Third, both IL-1β and IL-18 secretion in response to E. coli infections was dramatically diminished in GBPchr3−/− BMDMs." (PMID 28974614, 2017). "In this study, we examined the effect of E. coli infection on the expression of the pro-inflammatory cytokines IL-1β, IL-6, and TNF-α in PRNP-knockout macrophages." (PMID 25058617, 2014). "E. coli infection increased IL-1β and TNF-α levels in the jejunum of broilers." (PMID 40963585, 2025). "However, at 12 and 24 h post-infection, PGD2 significantly downregulated the secretion of TNF-α, IL-1β, and IL-8 compared to the E. coli infection group, while the secretion of IL-6 and IL-10 remained elevated (P < 0.01)." (PMID 40874199, 2025). "In this study, we observed that Ybt promotes chromosome aggregation in intestinal epithelial cells caused by E. coli infection, resulting in a large number of cells being TUNEL positive, and a substantial increase in inflammatory IL-1β and IL-18 in intestinal epithelial cells." (PMID 37511208, 2023). "Collectively, our data implicate that CVB3 infection could increase the susceptibility of mice to E. coli infection, possibly by inhibiting the activation of the NLRP3 inflammasome and the production of IL-1β." (PMID 37243164, 2023). "Remarkably, the double challenge of high glucose and infection provoked a pathogen-specific attenuated placental inflammatory response in the hyperglycemic condition, mainly denoted by reduced TNF-α and IL-6 secretion after S. agalactiae infection and by IL-1β after E. coli infection." (PMID 36982317, 2023). "Furthermore, the attenuated inflammatory response in hyperglycemic placenta was pathogen-specific, with the suppression of TNF-α and IL-6 or IL-1β after S. agalactiae and E. coli infection, respectively." (PMID 36982317, 2023). "Furthermore, E. coli infection also resulted in a significant up-regulation in the protein levels of IL-1β and IL-18, while these effects were attenuated by Z. morio hemolymph or gentamicin administration." (PMID 36362066, 2022). "Moreover, the protein levels of IL-1β and IL-6 were lower and located in the superficial umbrella cells in diabetic mice bladders 24 h post E. coli infection." (PMID 36127330, 2022). "In a mouse model for S. aureus and E. coli infections, animals with E. coli infection showed significantly greater serum levels of the cytokines interleukin (IL)-1α, IL-1β, IL-6, monocyte chemotactic protein (MCP)-1, and macrophage inflammatory protein (MIP)-1α than S. aureus-infected mice." (PMID 34247606, 2021). "Similarly, study showed that adding LAB prevented E. coli infection and depressed the expression of proinflammation cytokine IL-8 and IL-1β of endometrial cells in vitro." (PMID 31997024, 2020). "Moreover, Ager−/− BMDM was also resistant to LPS electroporation or E. coli infection-induced cytotoxicity, IL-1β release, and IL-18 release in LPS-primed BMDMs." (PMID 31440260, 2019).
E. coli infection (continued). "ASC knockout diminished, but did not completely prevent, increased production of IL-1β and IL-18 and cell pyroptosis associated with E. coli infection, whereas pre-incubation with L. rhamnosus GR-1 inhibited this increase." (PMID 30087667, 2018). "In addition to its basal expression during development, GFP is also induced following E. coli infection in Tg(il1b:GFP-F) fish, which parallels endogenous il1b induction." (PMID 24973754, 2014). "Previous studies have shown that taking BBR can significantly alleviate the increase in serum IL-6, IL-1β, and TNF-α caused by Escherichia coli infection in chicks and alleviate the increase in IL-6, IL-8, and TNF-α expression in the intestine caused by Escherichia coli infection in weaned piglets." (PMID 40829428, 2025). "Levels of TNF-α (164 ± 8.3 pg/mL versus 123 ± 3.4 pg/mL, p < 0.001), IL-1β (65 ± 3.3 pg/mL versus 38 ± 2.7 pg/mL, p < 0.001), IL-8 (173 ± 6.3 pg/mL versus 129 ± 8.4 pg/mL, p < 0.001) were found to be augmented in S. aureus infection as compared with E. coli infection." (PMID 36298513, 2022). "In LPS or E. coli infection, Txnip-deficient macrophages manifest the partial decrease of active caspase-1 and IL-1β production, which might result from increased S-nitrosylation of NLRP3 inflammasome components that hinder IL-1β maturation." (PMID 31620121, 2019). "We observed that 24 h of PGD2 pretreatment followed by 6 h of E. coli infection increased pro-inflammatory cytokines (TNF-α, IL-1β, and IL-8) secretion in BMDMs." (PMID 40874199, 2025). "L. fermentum MC018 reduced the levels of IL-1β, IL-6, and TNF-α in intestinal tissues following E. coli infection." (PMID 40963585, 2025). "Our results showed that E. coli infection triggered both a strong inflammatory response, via NF-κB pathway activation and pro-inflammatory cytokine (TNF-α, IL-6, IL-1β) release, and apoptotic cell death." (PMID 41302013, 2025). "In this study, E. coli infection resulted in elevated levels of TNF-α, IL-1β, and IL-6, accompanied by decreased IL-10 levels in the JM group, consistent with findings in animals induced with bacterial and Lipopolysaccharide challenges." (PMID 39199953, 2024). "Interestingly, when uroepithelial cells failed to release IL-1β in the presence of COX-2 inhibitor and even during E. coli infection, we observed increased expression of IL-1β in macrophages and NK cells which might be assumed to compensate the loss of effect in an in vivo model." (PMID 37697284, 2023). "To further elucidate the mechanism of pyroptosis induced by E. coli infection, we mined the dataset (GSE124917) in the GEO database and found that E. coli infection significantly upregulates NLRP3, caspase-1, GSDMD, and IL-1β." (PMID 37511208, 2023). "Our results showed that pretreatment with different doses of L. plantarum 17–5 reduced the expression of IL1β, IL6, IL8, TNFα, COX2, iNOS, CXCL2 and CXCL10 during E. coli infection." (PMID 35764986, 2022). "We found that GlcN (10 and 30 mM) significantly inhibited IL-1β secretion induced by ATP, nigericin, monosodium urate crystals (MSU) and E. coli infection." (PMID 30944389, 2019). "The knockdown of duNLRP3 significantly impaired the mRNA expression levels of IL-1β, IL-18, and TNF-α induced by E. coli infection (P < 0.01)." (PMID 30349536, 2018). "In this study, we demonstrated the role of duNLRP3 in the expression of inflammatory cytokines IL-1β, IL-18, and TNF-α mRNA after E. coli infection." (PMID 30349536, 2018). "The results show that IL-1β, IL-18, and TNF-α in the liver, spleen, and brain of the NLRP3-lentiviral vector-injected group mostly increased after E. coli infection." (PMID 30349536, 2018). "We also detected the mRNA expression levels of inflammatory cytokines IL-1β, IL-18, and TNF-α in the liver, spleen, and brain after the E. coli infection." (PMID 30349536, 2018).
E. coli infection (continued). "We found that GBP2−/− BMDMs mimicked GBPchr3−/− BMDMs in their unresponsiveness to E. coli infections, as measured by LDH release as a marker of cell death and secretion of IL-1β and IL-18." (PMID 28974614, 2017). "E. coli infection significantly induced PGE2 synthesis in BMDMs, which exacerbated the inflammatory response and tissue damage via NF-κB and MAPK signaling pathways, elevating TNF-α, IL-1β, IL-6, and IL-8." (PMID 40666730, 2025). "The expression levels of interleukin 1 b (IL1B), IL6, tumor necrosis factor a (TNFA), interleukin-8 (CXCL8), and defensin beta 2 (DEFB2) genes in the endometrium of the GE group were upregulated (p < 0.05) after E. coli infection." (PMID 40075974, 2025). "Systemic E. coli infection induced substantial increases in IL-6, IFN-γ, TNF-α, and IL-1β." (PMID 41309396, 2025). "Our study demonstrated that Ybt-induced E. coli infection led to intestinal epithelial cell pyroptosis via the NLRP3 pathway, resulting in the release of large amounts of IL-1β and IL-18, which promoted gut inflammation and contributed to E. coli-induced intestinal damage." (PMID 37511208, 2023). "Furthermore, E. coli infection resulted in an increase in the mRNA expression of the pro-inflammatory factors TNF-α and IL-1β in the mammary gland, but this increase was attenuated by either Z-d14CFR or gentamicin treatment (p < 0.001)." (PMID 35563007, 2022). "The expression of TLRs in BF of chicks treated with HQD were up-regulated, indicating that HQD regulates the anti-infection ability by increasing the mRNA levels of TLR4, -5 and -15, further decreasing the serum LZM and IL-1β, TNF-α, IL-10, IL-6 level of chicks suffered E. coli infection." (PMID 36198724, 2022). "The present study therefore compared the basal and LPS-stimulated production of IL-1B and NO between the macrophages obtained from Holstein cows which did or did not succumb to an E. coli infection." (PMID 36009735, 2022). "In response to E. coli infection, neither Nlrp3 nor Il1b mRNA levels were decreased in Casp6−/− BMDMs compared with those in WT BMDMs." (PMID 34740613, 2021). "We hypothesized that during E. coli infection, the activity of NLRP3 and NLRC4 inflammasomes is differentially regulated by L. rhamnosus GR-1, inducing maturation of IL-1β and IL-18 or cell pyroptosis, depending on ASC." (PMID 30087667, 2018). "In addition, the mRNA expression levels of IL-1β, IL-18, and TNF-α induced by E. coli infection were significantly up-regulated in comparison with the NC-lentiviral vector group (P < 0.01)." (PMID 30349536, 2018). "It must be noted that ASC deficiency reduced, but did not abolish, caspase-1 processing, IL-1β and IL-18 maturation, and cell pyroptosis during E. coli infection." (PMID 30087667, 2018). "All these results suggest that duNLRP3 could induce the mRNA expression of IL-1β, IL-18, and TNF-α during E. coli infection, shows that duNLRP3 plays an important regulatory role in the innate immune response to E. coli." (PMID 30349536, 2018). "Abundance of the chemical compound LPS has not been measured, but E. coli infection had increased the mRNA concentrations encoding TNF by 8 fold and IL1B by almost 14 fold." (PMID 28684793, 2017). "Furthermore, the levels of IL-1β, IL-6, and TNF-α increase in mammary glands with E. coli infections in mice." (PMID 23626786, 2013). "Based on our findings, BLP could be contributed to attenuating the proinflammatory cytokine (TNF-α and IL-1β) and chemokine (RANTES) production and enhancing anti-inflammatory cytokine (IL-10) production in mouse sera, lungs, and livers after E. coli infection or LPS stimulation." (PMID 36916913, 2023). "E. coli infection of SC-236 treated dHL-60 cells did not alter the expression of IL-1β." (PMID 37697284, 2023).
E. coli infection (continued). "Moreover, the results demonstrate the expression of the cytokines IL-1β and IL-6, cell mediated responses as well as APEC-specific T-cell response dominated by IFN-γ-producing CD8α+ and TCR-γδ+ subsets to be triggered against colibacillosis." (PMID 37261344, 2023). "At 3 h after E. coli infection, the qPCR results showed that overexpression of mgU2-30 led to a significant increase in the levels of pro-inflammatory cytokines IL-6, TNF-α, and IL-1β, whereas knockout of mgU2-30 did not cause an increase in the level of these cytokines in hBMECs." (PMID 34980188, 2022). "In these studies, E. coli infection increased the concentrations of pro-inflammatory cytokines (IFN-γ, TNF-α, IL-1β, IL-6 and IL-8) and decreased the concentrations of anti-inflammatory cytokine (IL-4), indicating that E. coli could induce inflammation in mice through regulation of cytokines." (PMID 33676495, 2021). "In agreement, we further found that E. coli infection induced a transient increase (after 1 and 6 h) in brain levels of the pro-inflammatory cytokine tumor necrosis factor α (TNF-α), whereas levels of interleukin 1β (IL-1β) were comparable between groups at the evaluated timepoints." (PMID 30975983, 2019). "Thus, the decreased levels of IL-1β after E. coli infection but not as a result of S. agalactiae’s presence in the hyperglycemic placenta could be explained by the inhibition of the inflammasome complex formation or caspase 1 activation." (PMID 36982317, 2023).
Cachexia (73 papers, 2007 to 2026). Severe weight loss, wasting of muscle, loss of appetite, and general debility related to a chronic disease. "Pro-inflammatory cytokines, notably tumor necrosis factor-alpha (TNF-α), interleukin-6 (IL-6), and interleukin-1 beta (IL-1β), significantly contribute to cachexia pathophysiology by promoting muscle wasting and fat loss." (PMID 40133874, 2025). "Cachexia is also associated with excessive levels of IL-1β, which cause muscle wasting and anorexia in affected patients." (PMID 40869331, 2025). "In our study, an increase in IL-1β levels in the plasma of MM patients was associated with an increase in the risk of developing cachexia." (PMID 38610941, 2024). "IL-1α and IL-1β, cytokines of the interleukin 1 family, have also been linked to the development of cachexia and muscle mass depletion in the context of malignancy or infectious diseases." (PMID 35743911, 2022). "This cytokine is mainly secreted by macrophages, it causes fever by direct action or through IL1B secretion, and has been implicated in the induction of cachexia." (PMID 36105284, 2022). "The NLRP3 inflammasome is known to become activated upon metabolic disturbances and boosts pro-inflammatory immune reactions via IL-1β, which not only drives myocardial remodeling but also is the hallmark of cachexia, metabolic de-regulation." (PMID 35967380, 2022). "Cytokines produced by immune or tumor cells, including TNF-α, IL-1β, and IL-6, have been proven to cause muscle atrophy in cachexia patients and animal models." (PMID 34093209, 2021). "IL-1β gene is located on chromosome 2q14 within a 360-kb region and it has been shown that key polymorphisms, IL-1beta +3954, are a risk factor for the development of cachexia in patients with gastrointestinal cancers." (PMID 33907915, 2021). "Tumor derived pro-inflammatory cytokines including TNF, interferon-γ (IFN-γ), and several interleukins (IL-6, IL-1β) have been associated with the development and progression of cachexia." (PMID 34621740, 2021). "The autostimmulatory effect of IL-1β is the best studied so far, and its role during disease-associated anorexia and cachexia was intensively reviewed." (PMID 32024569, 2020). "A more recent study demonstrated how IL-1 beta (IL-1β) increased SM catabolism in a rodent model of CC by promoting a cachexia-associated gene expression pattern in the hypothalamic–pituitary–adrenal (HPA) axis, differently from IL-6 and IL-1α." (PMID 32195193, 2020). "High levels of proinflammatory cytokines including IL-1β are associated with muscle wasting and cachexia." (PMID 26913600, 2016). "Cytokines, including Tumor Necrosis Factor (TNF)/cachectin, interleukin (IL)-1α, IL-1β, interferon-γ, and IL-6 have been implicated in cachexia both through experimental manipulation in mouse models and by association of serum levels in patients with cachexia." (PMID 21799891, 2011). "We presently demonstrate a higher protein content for TNF-α and IL-1β in the hypothalamus of rats with anorexia-cachexia associated with cancer." (PMID 21861927, 2011). "Logistic regression adjusted for actual weight, carcinoma location and stage, the IL-1β+3954 CT genotype was associated with an odds ratio of 2.512 (95% CI, 1.180 – 5.347) for cachexia." (PMID 17359523, 2007). "In a logistic regression analysis adjusted for actual weight, carcinoma location and stage, the IL-1B+3954 CT genotype was associated with an odds ratio of 2.512 (95% CI, 1.180 – 5.347) for cachexia." (PMID 17359523, 2007). "Moreover, determining the level of IL-1β with other parameters increases the diagnostic utility in assessing the risk of developing cachexia." (PMID 38610941, 2024). "Moreover, patients with the CC genotype of the IL1B gene had significantly more than 8-fold higher risk of cachexia (OR = 8.44; p = 0.0003)." (PMID 38610941, 2024). "Similarly, a significantly more than 8-fold higher risk of cachexia was noted in patients with higher IL-1β plasma levels (OR = 8.40; p = 0.0001)." (PMID 38610941, 2024).